ALB (albumin)
Diseases named in the same sentence as ALB in open-access papers (continued):
Sharing a sentence is not in itself a finding about the gene and the disease.
Cirrhosis (continued). "Using the search terms “Pichia pastoris” and “clinical allergy” identified 34 papers, including one with a direct administration of recombinant human serum albumin made in this yeast, injected three times over 3 days, in 423 cirrhosis patients with ascites or edema." (PMID 39114650, 2024). "Moreover, serum albumin levels are an integral component of the CTP score that assesses the prognosis of patients with cirrhosis." (PMID 39597844, 2024). "However, effective serum albumin has been found to be a more insightful prognostic marker because it declines with increased cirrhosis severity." (PMID 38551716, 2024). "We created a highly accurate (c-index 0.87) long-term prognostic scoring system called the CACHEXIA score (Cancer including metastasis tumor, blood tumor, and bleeding from tumor, Albumin, Cirrhosis, High PS, EXtremely thin (i.e., low BMI), Increased CRP and BUN, Anemia (i.e., blood transfusion))." (PMID 38438534, 2024). "Albumin dosages for patients with cirrhosis vary based on specific clinical needs and conditions." (PMID 38551716, 2024). "Once established, our platform technology may also serve to diagnose disease progression and the monitoring of disease interventions such as the suppletion of albumin or the effective use of antibiotics in cirrhosis patients with infections." (PMID 39129954, 2024). "Currently, total serum albumin is utilised to understand the progression of cirrhosis severity." (PMID 38551716, 2024). "Currently, the MELD 3.0 has been proposed as a replacement for the MELD‐Na (similar to UKELD) and includes gender, serum albumin, and statistical interaction between albumin, creatinine, bilirubin, and serum sodium with superior prognostic discrimination in cirrhosis." (PMID 38961593, 2024). "Univariate analysis showed that significant factors associated with HCC after DAA were: history of treated HCC, cirrhosis, evidence of portal hypertension, higher AFP at the start or end of DAA therapy, higher bilirubin, lower platelets, lower albumin, and older age." (PMID 38273255, 2024). "Commonly used laboratory indicators are mainly albumin and prealbumin, which reflect the function of hepatic synthesis; albumin is more affected by exogenous supplementation, so albumin is of low value in assessing the nutritional status of cirrhosis." (PMID 39091687, 2024). "In cirrhosis, serum PC 32:0 correlated positively with bilirubin and negatively with albumin." (PMID 39125730, 2024). "In addition, these altered forms of albumin can indicate progression into other complications of cirrhosis such as HRS and SBP and allow for more prompt treatment initiation." (PMID 38551716, 2024). "As albumin is synthesized in the liver, conditions such as cirrhosis also need attention." (PMID 38610630, 2024). "Recently, the potential diagnostic value of Gas6 and its albumin ratio was evaluated in patients with biopsy-proven chronic liver diseases, revealing that Gas6/albumin ratio possesses high accuracy in detecting advanced fibrosis and cirrhosis and predicts the severity of liver disease." (PMID 38298195, 2024). "In the case of cirrhosis, the liver’s synthetic function is impaired, leading to a decrease in albumin synthesis, which may result in hypoproteinemia." (PMID 39003447, 2024). "Albumin levels fall as the synthetic function of the liver declines with worsening cirrhosis." (PMID 39335727, 2024). "Indeed, serum albumin level is generally reduced in patients with cirrhosis and has been shown to be an independent predictor of mortality." (PMID 38961593, 2024). "Albumin has multiple functions, including volume expansion, antioxidant, immunomodulation, and anti-inflammatory effects, which can be used for the treatment of decompensated cirrhosis." (PMID 38191888, 2024). "Moreover, network mapping also predicts response to intravenous albumin in patients hospitalized with decompensated cirrhosis." (PMID 38961593, 2024).
Cirrhosis (continued). "The role of albumin in cirrhosis extends beyond its oncotic functions, such as plasma volume expansion, to diverse non-oncotic properties, including substance binding, antioxidant actions, inflammation modulation, immune response, cardiac function enhancement, and endothelial integrity restoration." (PMID 38139434, 2023). "Albumin is synthesised in the liver and, therefore, its concentration is reduced in cirrhosis." (PMID 37822786, 2023). "Therefore, albumin-corrected total serum calcium is of specific importance, as it can serve as a red flag indicating disease progression in cirrhosis patients following SARS-CoV-2 infection." (PMID 37371636, 2023). "However, there remains a need for large, randomized trials concerning the use of albumin in patients with decompensated cirrhosis and AKI." (PMID 39132612, 2023). "Recent studies of human albumin in decompensated cirrhosis have yielded mixed results." (PMID 38139434, 2023). "Moreover, the data of serum biochemical indicators in rats showed that the levels of ALT, AST, and ALP in rat serum were remarkably increased in the cirrhosis group while the ALB level was lowered compared with the control group." (PMID 37273916, 2023). "Therefore, this study conducted sensitivity analyses after excluding patients with severe liver disease or cirrhosis and those who had been infused with albumin within 48 h of admission to the hospital, and still ended up with the same conclusion." (PMID 38114922, 2023). "One study showed that albumin administration improved mortality in patients with cirrhosis and HE." (PMID 37770848, 2023). "Albumin is crucial in managing cirrhosis-related complications, such as ascites, HRS, AKI, and SBP." (PMID 38139434, 2023). "Low albumin levels secondary to the impaired synthetic capacity of the liver or protein malnutrition have a significant prognostic role in patients with cirrhosis and are associated with negative outcomes." (PMID 36765884, 2023). "Furthermore, the structure of albumin is also altered in cirrhosis, mainly via oxidation, plasma levels of oxidized albumin increase further in ACLF." (PMID 37822786, 2023). "The important function of HDL, similar to that of albumin, is to neutralize LPS;109 therefore, its low abundance in cirrhosis could be a reason for higher LPS serum concentrations and low-grade inflammation." (PMID 37822786, 2023). "A large randomized clinical trial discovered that long-term administration of albumin could improve survival in patients with decompensated cirrhosis." (PMID 37539053, 2023). "The efficacy of albumin therapy varies in different cirrhosis scenarios." (PMID 38139434, 2023). "The only independent factor predicting infection in cirrhosis was low albumin level." (PMID 37870985, 2023). "For example, in diseased livers with cirrhosis, albumin levels are drastically reduced." (PMID 38155919, 2023). "Clinical outcomes in cirrhosis have been shown to correlate with reduced albumin concentrations." (PMID 37013893, 2023). "Therefore, CAR, a combined marker of CRP and albumin, is suggested to be a crucial indicator in patients with cirrhosis." (PMID 36983211, 2023). "Similarly, IGF-1 administration improved liver function (increased albumin, total protein, and coagulation factor levels) and reduced oxidative liver damage and fibrosis in rat models with CCl4-induced cirrhosis." (PMID 37554499, 2023). "We showed that the accuracy of sAxl to detect significant to advanced fibrosis, and cirrhosis could be further improved by applying a sAxl/albumin ratio (sAxl/alb), making it a suitable screening parameter especially in a situation where VCTE is not available." (PMID 37532736, 2023). "Furthermore, it is known that the advanced stage of cirrhosis is characterized by impaired hepatocyte function, which leads do decreased albumin levels in patients and making albumin an important prognostic marker for cirrhotic patients." (PMID 36639512, 2023).
Cirrhosis (continued). "CRP and albumin are closely related in patients with cirrhosis." (PMID 36983211, 2023). "In cases of cirrhosis resulting in low albumin, the amount of zinc stored in the liver may be reduced, possibly resulting in increased blood zinc levels." (PMID 36701704, 2023). "In this study, we use a nationwide electronic health record database to study patterns of treatment with albumin in patients hospitalized with cirrhosis and AKI and to also examine the association of early administration of albumin with hospital LOS and in-hospital mortality." (PMID 39132612, 2023). "LS, hepatic echo, splenomegaly, GP73, total bilirubin, prothrombin time, prothrombin time activity and INR in the cirrhosis group were higher than those in the non-cirrhosis group, while ALB, PLT count and complement C4 in the cirrhosis group were lower than those in the non-cirrhosis group." (PMID 37747028, 2023). "The “human Albumin for the treatmeNt of aScites in patients With hEpatic cirrhosis” (ANSWER) study showed that human albumin significantly improved 18-month overall survival, eased ascites management, and reduced severe complications compared to standard medical treatment." (PMID 38139434, 2023). "At assessment for LT, the vast majority of children already were experiencing complication of cirrhosis, and the majority of children needed medical assistance (nutritional support, hospitalization, transfusion of albumin or blood) while waiting for transplantation." (PMID 35456234, 2022). "Genome‐wide association study (GWAS) summary statistics were extracted from seven studies (>1.7 million participants) for variants near ACVR2A, ALB, CIDEB, FOXO1, GPAM, NEAT1 and TNRC6B for: aminotransferases, liver fat, HbA1c, diagnosis of NAFLD, ARLD and cirrhosis." (PMID 35474605, 2022). "Therefore, further well-designed studies need to be carried out on midodrine in addition to albumin for optimal clinical benefits among patients with ascites due to cirrhosis." (PMID 36060403, 2022). "Univariable logistic regression analysis of clinical variables associated with in-patient mortality for patients with cirrhosis included elevated WBC count, higher INR, higher total albumin, and higher MELD-Na score, Child-Pugh Score B or C, and the presence of hepatic encephalopathy." (PMID 36099308, 2022). "In conclusion, to our knowledge, this is the first study to indicate that rifaximin may improve the structure of circulating albumin in patients with cirrhosis." (PMID 36555935, 2022). "Overall, the cirrhosis group was associated with higher mean age, white blood cell count (WBC), international normalized ratio (INR), total bilirubin (TB), MELD score, and MELD-Na score, but lower albumin and blood sodium levels." (PMID 36618679, 2022). "As hyperammonemia directly induces oxidative stress, rifaximin may improve the structure of circulating albumin in patients with cirrhosis by reducing serum ammonia levels." (PMID 36555935, 2022). "Moreover, cirrhosis patients receiving short-term intravenous albumin have a decreased interleukin-6 level showing an increase in systematic inflammation." (PMID 36721617, 2022). "Furthermore, the functions of serum albumin, such as antioxidant and detoxification capacity and the ability to chelate metal ions, were compromised in patients with cirrhosis." (PMID 34983435, 2022). "Furthermore, accumulating evidence shows that serum albumin levels were low in patients with advanced and decompensated cirrhosis, due to a reduction in the hepatocyte mass." (PMID 35923200, 2022). "In this study, our results revealed that rifaximin reduces serum ammonia levels and may improve the structure of circulating albumin by reducing oxidized albumin in patients with cirrhosis." (PMID 36555935, 2022). "Thus, further large-scale prospective studies are essential to conclude that rifaximin improves the structure of circulating albumin in patients with cirrhosis." (PMID 36555935, 2022).
Cirrhosis (continued). "However, it is possible that the prognostic value of the CAR varies according to the type of patient, for example, in patients with low albumin values, such as patients with cirrhosis or nephrotic syndrome." (PMID 36006278, 2022). "In this retrospective study of individuals with cured HCV-related cirrhosis, we showed that during the follow-up following viral eradication, a significantly higher proportion of patients had improved serum albumin levels as a biochemical marker of liver synthesis (66%)." (PMID 36009789, 2022). "Cirrhotic patients were found to have lower serum levels of cholesterol, albumin and platelet, which should be held as manifestations of cirrhosis rather than risk factors." (PMID 35745223, 2022). "Albumin is exclusively synthesized by the liver, and low albumin levels may be a marker of advanced diseases in chronic liver inflammation or cirrhosis." (PMID 36364725, 2022). "Most importantly, it has been suggested that serum levels of ‘effective’ albumin may be a better prognostic indicator than ‘total’ albumin in patients with decompensated cirrhosis." (PMID 33925831, 2021). "Recently, the ANSWER trial showed for the first time that long-term albumin administration, on top of a standard diuretic therapy, could be a novel therapeutic approach for patients with cirrhosis and grade 2–3 uncomplicated ascites." (PMID 34830508, 2021). "Indeed, correlations between albumin’s decreased functional capacity and mortality in patients suffering from decompensated cirrhosis have been established, with the level of damaged albumin being a good predictor of disease progression." (PMID 34836265, 2021). "Serum albumin levels fall as the synthetic function of the liver declines with worsening cirrhosis." (PMID 34198972, 2021). "Moreover, only cirrhosis, albumin level, and creatinine level had been identified as factors independently associated with post-treatment mortality." (PMID 33777520, 2021). "However, large-cohort clinical data on treatment with albumin in decompensated cirrhosis are still scarce and somewhat ambiguous." (PMID 34836265, 2021). "However, there still are debates on the benefit of albumin in patients with cirrhosis over the long term." (PMID 34571946, 2021). "A reduced serum concentration of albumin is a common feature in patients with cirrhosis." (PMID 34068295, 2021). "FFM may be correlated with albumin level in patients with cirrhosis, but it should be recorded and assessed for each individual, like PhA." (PMID 34898583, 2021). "Notably, a recent clinical trial presented that the long-term albumin administration to patients with cirrhosis reduced systemic inflammation and the cumulative incidence of complications of cirrhosis, including SBP and non-SBP bacterial infections." (PMID 34571946, 2021). "Albumin may be effective in preventing overt HE in patients with decompensated cirrhosis, as demonstrated by a large retrospective study and a recent meta-analysis." (PMID 34575157, 2021). "Age >75 years, cirrhosis, underlying liver disease, left hepatectomy, right hepatectomy, benign disease, Child-Pugh class A/B, and pre-operative albumin <3.5 g/dL were not risk factors for bile leakage after hepatectomy without biliary reconstruction." (PMID 34790696, 2021). "Decreased serum albumin in patients with cirrhosis binds fewer prostaglandin E2 (PGE2) resulting in increased bioavailability of PGE2, which dampens the macrophage response to LPS, indicating that albumin may promote immune functions in some ways." (PMID 34571946, 2021). "Indeed, with its oncotic properties, albumin can counteract effective hypovolemia, a central event in cirrhosis pathophysiology." (PMID 34830508, 2021). "Furthermore, decreased albumin levels are predictive of morbidity and mortality postoperatively, as well as in disease states such as cirrhosis, renal failure, burns, malignancy, and autoimmune disorders." (PMID 33592030, 2021).
Cirrhosis (continued). "However, in multivariate analysis, E/e′ ≥ 10 (HR = 2.72, 95% CI 1.07-6.9, p = 0.03) and serum albumin (HR = 0.32, 95% CI 0.14-0.7, p < 0.01) were found to be independent predictors of mortality in decompensated cirrhosis patients." (PMID 34900353, 2021). "In patients with acutely decompensated cirrhosis, albumin administration has been shown to reduce inflammation, and may therefore involve a direct effect of albumin on leukocytes." (PMID 33925831, 2021). "Therefore, we aimed to capture the perceptions regarding the management of PH and the use of albumin among physicians caring for patients with cirrhosis in Austria in comparison with current Billroth III recommendations." (PMID 33270161, 2021). "Cirrhosis and serum albumin were proven to have a tight relation with CCNB1's expression." (PMID 34337056, 2021). "Moreover, the current study identified cirrhosis, low albumin levels, and high creatinine levels as indicators of poor prognosis among the geriatric population after completing DAA therapy in real-world settings." (PMID 33777520, 2021). "The main rationale for long-term albumin substitution has, until recently, been the improvement of circulatory functions, which may prevent a range of acute complications of cirrhosis." (PMID 34836265, 2021). "As bacterial infection was identified as a critical determinant of rebleeding in cirrhosis by increasing portal pressure through vasoactive substances, the effect of albumin on systemic inflammation provides a potential theoretical basis for its role in reducing bleeding." (PMID 32576140, 2020). "Until a few years ago, the clinical effects of albumin were attributed almost exclusively to its capacity to expand plasma blood volume, thus counteracting the effective hypovolemia and the related hemodynamic alterations that characterize advanced cirrhosis." (PMID 32837825, 2020). "Moreover, higher abundance levels of both miRNAs were found in patients with a higher MELD-Albumin or ALBI score indicating advanced stages of liver fibrosis/cirrhosis." (PMID 33490119, 2020). "In all of the patients, age, cirrhosis status, DM, albumin, AST, ALT, platelets, AFP 12M, APRI ≥ 0.90, APRI 12M ≥ 0.53, △APRI ≥ 0, FIB-4 ≥ 2.53, FIB-4 12M ≥ 2.56, and △FIB-4 ≥ 0 showed significant associations with HCC according to univariate Cox regression analysis." (PMID 32392752, 2020). "Liver tests including serum albumin, thrombin time, fibrinogen, platelet count and bilirubin were not different between those with and without cirrhosis, but larger studies are necessary to understand the effect of cirrhosis on COVID-19 infection and outcomes." (PMID 32403255, 2020). "This may affect, to some extent, the response of this complication to treatment with terlipressin and albumin in patients with advanced cirrhosis." (PMID 33102772, 2020). "However, correlation analyses of significantly abundant miRNAs to prognostic scores of advanced liver fibrosis/cirrhosis (MELD-Albumin and ALBI score) identified miR-29b-3p and miR-29c-3p to be best related to these scores." (PMID 33490119, 2020). "However, in many chronic and acute disease conditions, including advanced cirrhosis, the albumin molecule undergoes several post translational modifications, probably as a result of the proinflammatory and prooxidant microenvironment." (PMID 32837825, 2020). "Serum albumin levels were also lower in the cirrhosis group (P < .001)." (PMID 32176089, 2020). "Forty-two type-1 HRS patients with cirrhosis were treated with albumin and terlipressin." (PMID 32076410, 2020). "Patients with HCC showed higher alanine aminotransferase (ALT) (p = 0.023), higher aspartate aminotransferase (AST) (p < 0.001), lower platelet count (p < 0.001), lower albumin (p < 0.001) and higher total bilirubin (p = 0.018) compared to patients with cirrhosis." (PMID 33142893, 2020).